CD4 (CD4 molecule)
Diseases named in the same sentence as CD4 in open-access papers (continued):
Sharing a sentence is not in itself a finding about the gene and the disease.
tumor (continued). "We observed the same trend in the production of these cytokines at the protein level in the donor CD44hi CD4+ T cells during in vitro culture after isolation from the tumor." (PMID 34625113, 2021). "A complete understanding of the consequences of treatment on the intra-tumor cytokines would allow the establishment of more precise and efficient combinations of treatments, allowing modulation of CD4 T cells activity and increasing their effectiveness." (PMID 33498483, 2021). "Infiltration of CD4+ cells was heterogeneous in all tumor types and positively correlated with CD8-FOXP3+ and CD8-FOXP3-PD-1+ cell infiltration, suggesting that a considerable proportion of these cells are CD4+." (PMID 34799669, 2021). "IFN-γ produced by NK cells during early-phase immune responses can directly kill tumor cells and promote the differentiation of naive CD4+ T cells toward Th1 cells to facilitate cell-mediated immunity." (PMID 35003090, 2021). "TIMER database analysis showed that IGSF10 expression positively correlated with the proportion of tumor-infiltrating B cells, CD4+ T cells, CD8+ T cells, neutrophils, macrophages, and dendritic cells in the TCGA-LUAD dataset." (PMID 34351868, 2021). "TC-1 being a cold tumor model, CD4 and CD8 T cell infiltration combined represented less than 2% of tumor infiltrating CD45+ cells in vehicle treated mice." (PMID 34276686, 2021). "Without adiponectin, the selection function of TNC complexes is impaired, causing the escape of immature CD4+CD8+ thymocytes from thymus and their release into the blood circulation to facilitate tumor development in PyVT-AKO mice." (PMID 33727658, 2021). "It is well-known that CD8+ T cells can release perforin, granzymes, and granulysin to kill tumor cells, and CD4+ T cells play crucial roles in the regulation of adaptive immunity." (PMID 34262026, 2021). "PD-1hiCD39+ CD4 Tconv TILs encompassed tumor Ag–specific cells and provided help to CD8 T cells upon PD-1 blockade." (PMID 33332284, 2021). "Tumor T-cell infiltration (CD4 + and CD8 + effector T cells) was observed in both xenogeneic cell and GC treatment and the combined therapy further increased T-cell population, which reflects effective immunotherapy." (PMID 33156394, 2021). "Specific expression of PD-L1 on both tumor and myeloid cells in ST-EPN-RELA has been demonstrated, accompanied by high levels of PD-1 expressed by tumor-infiltrating T cells (both CD4 and CD8)." (PMID 34638438, 2021). "In this clinical corelative study we show that GBM microenvironment lacks directed anti-tumor effector phenotype of tumor infiltrating CD4+ helper T-cells, instead it is characterized by mixed effector phenotypes of multiple lineages." (PMID 34012510, 2021). "This in turn implies that, in the case of self-reactive anti-tumour CD4+ T cells, the self-tolerance mechanisms that would normally check such aberrant self-directed autoimmunity are either disrupted or negated within the TME." (PMID 32457487, 2021). "We next examined the relationship between the presence of TLS-B cells (assessed by IHC) and the phenotype of fresh intratumor CD4+ T cells (analyzed by flow cytometry) on the corresponding tumor biopsy." (PMID 33763071, 2021). "Bregs also encourage conversion of CD4+ into Treg and inhibit NK-mediated immunity, thus promoting tumour progression." (PMID 33860061, 2021). "Within tumor-infiltrating T cells, we identified CD4+ naïve T cells, CD4+ Tregs, CD4+ T helper 17-like T cells (Th17-like), CD8+ effector T cells, CD8+ exhausted T cells, and Natural Killer (NK) cells according to expression of their respective markers." (PMID 33953163, 2021). "CD4 memory phenotypes, in particular, a high CM: EM, have been found to correlate with poorer prognosis in other tumor types." (PMID 33717112, 2021). "IFN-gamma produced by tumor-specific CD4 and CD8 T cells prime macrophages, which can directly eliminate tumor cells." (PMID 35095857, 2021).
tumor (continued). "Recombinant human LYG1 protein (rhLYG1) can inhibit tumor growth by promoting the activation and IFN-γ production of tumor antigen-specific CD4+ T cells." (PMID 34262560, 2021). "Meanwhile, our results of immunohistochemistry at the tumor tissues found that both CD4+ and CD8+ cells significantly increased after RFA." (PMID 34616914, 2021). "Once in the lymph nodes, the dendritic cells activate tumor-specific CD4+ (Th1) T lymphocytes that produce IFN-γ." (PMID 33807260, 2021). "Treatment with an anti-CCR4 antibody selectively depleted effector Treg cells and efficiently induced tumor-antigen-specific CD4 and CD8 T cells." (PMID 34064410, 2021). "If originally these therapies mainly focused on exploiting CD8 T cells given their role in the direct elimination of tumor cells, increasing evidence highlights the crucial role CD4 T cells play in the antitumor immune response." (PMID 34064410, 2021). "Tregs—Tregs are a subset of CD4 T-cells that sustain an immunosuppressive tumor microenvironment via secretion of IL10 and TGFβ." (PMID 34944848, 2021). "Consistent with a role for adaptive immunity in regulating RM-9 tumor growth, altered tumor CD4+ T cell number and/or phenotype can affect the regulation of CD8+ T cell priming." (PMID 34604038, 2021). "We devised a simplified staining panel (DAPI, CD3, CD4, CD7, CD8, CD25, FoxP3, and PD-1) that captured the PD-1+ CD4+ T cells, tumor cells, and Tregs used to calculate the SpatialScore." (PMID 34795254, 2021). "The intratumoral immune response differed through its suppressive effect on the Th1-type cytokine production from CD4+ T cells; stress-increased tumor IL-12p40; this effect was consistent across age." (PMID 34604038, 2021). "It was also found that the level of inflammatory cell infiltration in the tumor microenvironment, including CD4+T cells, CD8+T cells, and CD19+B cells, was of certain significance in predicting the prognosis of GC." (PMID 34258299, 2021). "The expression of LILRB4 increased on CD4+ T cells with tumor progression (day 22 versus day 14 tumors) after B16/F10 challenge." (PMID 33974041, 2021). "CNs enriched in tumor and dendritic cells (CN-5, purple region) and tumor and CD4+ T cells (CN-8, yellow region) were present at significantly higher frequencies in responders post-treatment compared to other groups." (PMID 34795254, 2021). "We investigated Ag specificity of tumor-infiltrating CD4 Tconvs according to PD-1 and CD39 expression." (PMID 33332284, 2021). "Collectively, the results corroborated the previous finding that systemic tumor elimination by TLR9 agonists was partially CD4+ T cell-dependent." (PMID 35008305, 2021). "Several studies have also shown that the number and co-stimulation of tumor infiltrating lymphocytes (TILs), especially CD4+ T, CD8+ T cells, and dendritic cells (DCs), are indicators of curative effects." (PMID 33762577, 2021). "We then compared the methylation levels of Nqo-1 and Aldh1a3 in tumor infiltrated immune cells including TAMs, CD4+T cells, and CD8+T cells to BMDMs from the same KPC mouse." (PMID 34711804, 2021). "One study found that specific CD4 T cells with diverse receptor sequences were identified in 76% of assessed MCCs, and their concentration was 250-fold higher within the tumor environment than in the peripheral blood." (PMID 34208339, 2021). "Immune infiltration analysis showed that the expressions levels of COL3A1, RAC1, FN1, and SDC2 in CD4+T cells were significantly higher than those in tumor cells, especially regulatory T cell infiltration was significantly increased in BM tumors." (PMID 34229299, 2021). "High levels of all TIL subsets in hot‐spot areas (except CD4) were strongly associated with ER negativity, HER2‐positive tumors, and high tumor cell proliferation (by Ki67)." (PMID 34076969, 2021).
tumor (continued). "Upregulated within the tumor-infiltrating CD4+ T cells were heat shock proteins (HSPA1A and HSPA1B), Jun and FOS constituents (FOS, JUN, and JUNB), MHC-II molecules (HLA-DRB), and secreted molecules (CCL5, GZMA, and GZMK)." (PMID 33504936, 2021). "Our analysis indicated that HLA-G highly expressed in the tumor microenvironment have positive associations with tumour-infiltrating immune cells, including B cells, CD8+ T cells, CD4+ T cells, macrophages, DCs, and neutrophils." (PMID 34276642, 2021). "We and others have found that BI-ALCL tumor cells exhibit an activated CD4+ transcriptional profile with T regulatory features due to an IL10-, IL6-, IL13- and Eotaxin-rich cytokine microenvironment." (PMID 34944796, 2021). "Depletion of CD8+ cells negated beneficial effects of IL12-GEMy treatment, while depletion of CD4+ cells led to only partially reduced anti-tumor activity." (PMID 34305139, 2021). "The body’s immune functions of recognizing and eliminating tumor cells is insufficient, especially the CD4+T cells-mediated humoral immunity and CD8+ T cell-mediated cytotoxicity, which make abnormal cells proliferate and differentiate out of control." (PMID 34220863, 2021). "Therefore, a negative correlation of risk score with naïve B cells, naive CD4+ T cells, and resting mast cells and the positive correlation with monocytes suggests that the 18-gene signature is tightly associated with immune-active status in the tumor microenvironment." (PMID 35127715, 2021). "Together, these observations suggest that KVax synergizes with CA170 treatment to increase antitumor effector CD4+ T cells response and to decrease Treg-mediated immunosuppression in the tumor." (PMID 34302042, 2021). "In our hands, SB28 tumor cells did not express MHC-II, consistent with previous reports, so it is unlikely that effector CD4 T cells are directly mediating tumor rejection in this model." (PMID 34083417, 2021). "The expression level of APE1 and tumor-infiltrating CD4+ T cells was evaluated by immunohistochemistry (IHC)." (PMID 33676448, 2021). "Various immune cells such as CD8+ T cells, CD4+ type 1 T-helper (Th1) cells, natural killer (NK) cells, classically activated (M1) macrophages and mature dendritic cells (DCs) contribute to tumor elimination and thus are considered antitumorigenic." (PMID 33777801, 2021). "The immune microenvironment consisting of activated CD8+ and CD4+ T cells exert an anti-cancer role during tumor initiation but turn pro-tumorigenic during invasive growth." (PMID 34804909, 2021). "In contrast, CD4+Foxp3+ T cells, known as regulatory T cells (Tregs), which can hamper effective antitumor immunity, were significantly decreased in the tumor tissue of the ES-DSM + MW treated group." (PMID 34362890, 2021). "In contrast, however, it has been demonstrated that MCs can also affect the antitumor immunity via activation of various types of immune cells such as NK cells, dendritic cells (DCs), cytotoxic T (CD8+) cells, and T-helper (CD4+) cells at tumor sites." (PMID 34439898, 2021). "We further explored the relationship of SFRPs and tumor-infiltrating immune cells in GC and found that the expression of SFRPs was positively correlated with the infiltration of CD4+ T cells and macrophages." (PMID 34205081, 2021). "The majority of tumor-infiltrating lymphocytes were CD4 ‘helper’ T cells, and most CD8 T cells expressed their programmed cell death protein 1 (PD-1)." (PMID 34359785, 2021). "CD4+ T cells represent a major component of the adaptive immune system and have emerged as critical controllers of anti-tumor immunity in several types of cancer, including NSCLC." (PMID 34548096, 2021). "It is worth noting that we first found that LLPS regulatory factors were significantly correlated with tumor immune infiltration of B cells, CD4+ T cells, and CD8+ T cells in digestive system tumors." (PMID 35252219, 2021).
tumor (continued). "Several studies indicate that after implantation of radioactive 125I particles, the percentages of CD3+ T, CD4+ T, natural killer, and regulatory T cells significantly increased in the peripheral blood of tumor patients." (PMID 34268114, 2021). "Naive CD4+ T cells can also differentiate into various subsets to attain specialized effector functions, which play a vital role in tumor immunity." (PMID 35127715, 2021). "Val-boroPro can also promote dendritic cell (DC) trafficking and accelerate CD4+ and CD8+ T cell priming and expansion towards tumour-associated antigens in mice." (PMID 34771657, 2021). "Multiple preclinical studies of melanoma, lung, breast, and colon cancers have demonstrated tumor rejection by neoantigen-specific vaccination, where most of the epitopes were detected by CD4+ T cells." (PMID 34899753, 2021). "The expression profiles of the intratumoral CD4+ T cells can be used to analyze tumor-infiltrating T cell subsets and to predict how a patient will respond to cancer therapy." (PMID 33301062, 2021). "The characteristics of tumor immune infiltration, including the activity of CD4 and CD8 T cells, macrophages, and natural killer cells, are associated with immunotherapeutic efficacy." (PMID 34975871, 2021). "Since CD4+ T cells can independently kill tumor cells and promote the immune response through the regulation of other innate and adaptive immune cells, they were recently considered to play a more important role in the antitumor response." (PMID 34576115, 2021). "A recent investigation documented that resting memory CD4 T cells are one of the most enriched tumor-invasive immune cells in GC samples." (PMID 34708125, 2021). "In the B78 model, RT increases OX40 expression on tumor CD4+ cells and increases T cell activation in the spleen and TDLN when combined with CpG+OX40." (PMID 34868010, 2021). "Treg generation induced by IL-21high/PD-L1high tumor explant was further validated by cocultured with TAA-specific T cells (both CD4 and CD8)." (PMID 34026621, 2021). "Upregulation of LAG-3 by tumour-specific CD4+ and CD8+ T cells in Tregs infiltrating PCa lesions has been observed." (PMID 33921181, 2021). "After co-culture with tumour cells for 24 h, HLA-DR expression was higher increased in both CD4- and CD8-positive dCAR T cells." (PMID 33462245, 2021). "When tested, it was demonstrated that the combination of siIDO with photothermal therapy resulted in significantly reduced tumor growth, an increase in CD4+ and CD8+ tumor infiltrating lymphocytes, reduced T cell apoptosis and increased TNF-α and IFN-γ." (PMID 34688033, 2021). "Most of this review has focused on how CD8+ T cell activity is imperative to a strong anti-tumour response, with CD4+ T cells playing a supporting role in activating and maintaining the immune response." (PMID 34276688, 2021). "Circulating CD4+ and CD8+ memory T cells specific for the tumor-associated EBV proteins (EBNA1, LMP1 and LMP2) are mostly intact and functional, although their frequencies are somewhat lower than that observed in healthy donors." (PMID 33718235, 2021). "The number of TILs (CD45+, CD3+, CD4+, CD8+, and FOXP3+) and tumor‐associated macrophages (CD163+) was counted using immunohistochemistry on tissue microarray slides." (PMID 34076969, 2021). "In this review, we give an overview of the multifaceted role of CD4+ T cells in the anti-tumour immune response, with an emphasis on recent evidence that CD4+ T cells play a bigger role than previously thought." (PMID 32457487, 2021). "Next, flow cytometric analysis showed that the frequency of tumor-infiltrating IL-21+CD4+ T cells positively correlated with that of FOXP3+CD25+CD4+ T cells, which supported our immunohistochemical results." (PMID 34026621, 2021). "In contrast, the CD4+ TILs comprise several T cell subsets with different roles in tumor immunity, including the immunosuppressive Tregs." (PMID 34067849, 2021).
tumor (continued). "CD4+ Th1 cells have been found to be highly cytotoxic and equally capable of directly killing tumor cells as CD8+ T cells." (PMID 34681680, 2021). "Patient-derived NK treatment in vitro and in vivo in OC mouse models reduced tumour migration and invasion with the expansion of CD4+ and CD8+ T-cell populations, as well as IFN-γ production, leading to improved survival rates." (PMID 34944851, 2021). "The numbers of CD4+T cells were also markedly increased in the tumor microenvironment after DHA treatment." (PMID 34539408, 2021). "For instance, our results showed that immune cells, which play a vital role in tumor immunity, were significantly decreased in the high-risk group, such as CD8+ T cells, dendritic cells, B cells, and naive CD4+ T cells." (PMID 33854619, 2021). "The earliest efforts to induce CD4+ T cell responses against tumours were attempts to generate TH1-polarised CD4+ T cells by vaccination with peptide epitopes." (PMID 32457487, 2021). "Preclinical studies have demonstrated the potential contribution of various SCFAs in patient immunity, particularly butyrate, which has been theorized at high concentrations to foster anti-tumor effects via activation of effector CD4 and CD8 responses." (PMID 34256732, 2021). "This highlights that the tumor genetic features and the CD4 + T-cell infiltration are both factors of paramount relevance for the outcome of FL patients." (PMID 34267181, 2021). "The number of tumor-infiltrating CD4+ T cells and CD8+ T cells and their percentage of the total T cells from mice given the low-dose TSA-treatment were also higher than those from mice given vehicle alone." (PMID 33564072, 2021). "In general, CD8+ T cells are considered as mediators of direct tumor cell eradication, while CD4+ T helper lymphocytes, among numerous other functions, facilitate the activation and proliferation of CD8+ T cells." (PMID 34503109, 2021). "Taken together, ibrutinib-mediated inhibition of BTK in TAMs, MDSCs, DCs and B cells indirectly promote anti-tumor immunity by augmenting TH1 CD4 T cell response and increasing the infiltration of CD8 cytotoxic T cells and effector B cells into the TME." (PMID 34778053, 2021). "On the other hand, the following cell types were significantly present in the adjacent tumor tissues; naive B cells, activated and resting dendritic cells, M1 macrophages, activated and resting CD4 memory T cells and neutrophils." (PMID 33289508, 2021). "In particular, these studies focused on boosting CD4+ T cell-derived secretion of TH1-characteristic tumoricidal cytokines (e.g. IFNγ) as a readout of increased anti-tumour CD4+ responses." (PMID 32457487, 2021). "Menopausal status, estrogen receptor (ER), Ki-67 index, white blood cell (WBC), platelets (PLT), lactate dehydrogenase (LDH), and carbohydrate antigen 153 (CA153) had significant association with densities of tumor-infiltrating CD3+, CD8+, or CD4+ T cells." (PMID 33718143, 2021). "On the one hand, B cells can serve as positive mediators of the antitumour response through the production of tumour-reactive antibodies, promoting tumour killing by natural killer cells, phagocytosis by macrophages, and the priming of CD4+ and CD8+ cells." (PMID 33669038, 2021). "Most of the Sézary cells in the peripheral blood had lost CD4 expression, and we diagnosed the disease and evaluated the tumor burden by multicolor flow cytometry." (PMID 34123441, 2021). "CD8+ T cells are activated by CD4+ cells and migrate to the tumor site, exerting a cytotoxic effect." (PMID 34639167, 2021). "Consistent with the pathogenic feedback loop for IL-4, cultured cells derived from a plaque or a tumor lesion significantly increased the percentage of TOX+ CD4+ cells in the presence of recombinant IL-4." (PMID 34220814, 2021). "TIGIT is a co-inhibitory receptor expressed in lymphocytes, particularly in effector and regulatory CD4+ T cells, and in tumor cells." (PMID 33804419, 2021).